TFF2 (trefoil factor 2)
Description:
Inhibits gastrointestinal motility and gastric acid secretion. Could function as a structural component of gastric mucus, possibly by stabilizing glycoproteins in the mucus gel through interactions with carbohydrate side chains (By similarity).
Synonyms: SP; SML1
Tractability: Antibody: UniProt places it where antibodies can reach, with medium confidence; UniProt predicts a signal peptide or a membrane-spanning region; its Gene Ontology location is reachable by antibodies, with medium confidence.
Gene: Protein-coding gene on chromosome 21 (42,346,357 to 42,350,997, reverse strand). Ensembl gene ENSG00000160181.
Subcellular location: Secreted
Gene Ontology:
Molecular function: protein binding; CXCR4 chemokine receptor binding
Biological process: chemokine-mediated signaling pathway; maintenance of gastrointestinal epithelium; negative regulation of gastric acid secretion
Cellular component: extracellular region
Genetic constraint (gnomAD): Loss-of-function variants: 19 observed, 15.66 expected, observed/expected ratio (o/e) 1.21, 90% interval 0.84 to 1.74. The upper end of that interval is the gene's LOEUF score, 1.74, which puts it in group 6 of 6, group 1 being the genes least tolerant of losing a copy. Missense variants: 168 observed, 165.38 expected, observed/expected ratio (o/e) 1.02, 90% interval 0.89 to 1.15. Synonymous variants: 61 observed, 62.7 expected, observed/expected ratio (o/e) 0.97, 90% interval 0.79 to 1.2.
Homologues: Orthologues: chimpanzee TFF2 (99% identical), macaque TFF2 (87% identical), mouse Tff2 (81% identical), rat Tff2 (78% identical), guinea pig TFF2 (78% identical), pig TFF2 (74% identical), dog TFF2 (71% identical), tropical clawed frog tff3.8 (41% identical), tropical clawed frog tff3 (22% identical). Paralogues in human: TFF1 (27% identical), TFF3 (25% identical).
Diseases named in the same sentence as TFF2 in open-access papers:
TFF2 is named in the same sentence as 142 diseases in open-access papers, as found by Europe PMC text mining. Sharing a sentence is not in itself a finding about the gene and the disease. The quoted sentences say what the papers report.
gastric cancer (35 papers, 2011 to 2025). A primary or metastatic malignant neoplasm involving the stomach. "In order to discover the function of TFF1 MS and TFF2 MS in gastric cancer, wild-type (WT) and mutation-type (MUT) plasmids were constructed." (PMID 36428568, 2022). "Followed by the mutation of TFF1 MS and TFF2 MS, the protein and mRNA expression were reverted in two gastric cancer cell lines." (PMID 36428568, 2022). "Organoids have also been useful in the study of the progression from gastritis to gastric cancer characterised by parietal cell loss and development of spasmolytic polypeptide/Trefoil Factor (TFF) 2-expressing metaplasia (SPEM) in its early stages." (PMID 35269931, 2022). "The difference expression of PAR4 and TFF2 was detected in various tumors, such as the pancreas cancer, lung cancer and gastric cancer, and this difference expression was associated with tumor cell growth, migration, invasion and angiogenesis." (PMID 25876034, 2015). "Certain studies have previously reported that TFF2 expression is upregulated in gastric cancer tissues and that the overexpression is associated with cancer invasion, metastasis and a poor prognosis." (PMID 24765170, 2014). "In the present study, by RT-PCR, qPCR, western blotting and immunohistochemical assays, the expression of TFF2 was shown to be frequently downregulated in gastric cancer tissues compared with the associated normal mucosa." (PMID 24765170, 2014). "The dysregulation of TFF2 expression has been associated with gastric cancer cell migration, invasion and resistance to apoptosis." (PMID 24765170, 2014). "Similarly, we discovered that the mRNA and protein expression of TFF2 were downregulated in tumor tissues and TFF2 was associated with the prognosis of gastric cancer patients based on TCGA database." (PMID 36428568, 2022). "Trefoil factor 2 (TFF2) plays a protective role in gastric mucosa and may be involved in the progression of gastric cancer, but the detailed functions and underlying molecular mechanisms are not clear." (PMID 24765170, 2014). "The evidence that TFF2 expression was found to decrease is consistent with the results of previous studies, and decreased TFF2 expression is associated with the proliferation and malignant transformation of gastric cancer mucosa." (PMID 24765170, 2014). "The expression pattern of Tff2, which is a member of the newly discovered protective factor of gastrointestinal mucous, may be associated with gastric cancer." (PMID 21799680, 2011). "The combined genotype such as ITGA5-1160/ITGB1-1949/ITGB1 + 31804 as T/A/C carriers and COX-2-1195/IL-10-592 as G-carrier/AA, or even more specifically combined with RUNX3 + 492/TFF2-308, may thus serve as a host factor to identify the risk group of gastric cancer for an early H. pylori eradication." (PMID 25884934, 2015). "Some researchers use tissue biomarkers (TFF2, mir-124a-3p, etc.), innovative blood biomarkers, and other low-cost markers (CEA, CA19-9, MUC16, etc.)to predict and evaluate the risk of gastric cancer." (PMID 36052291, 2022). "Taken together, our findings suggested that TFF1 and TFF2 were both downregulated in gastric cancer, and their mRNA expressions were silenced by DNA methylation." (PMID 36428568, 2022). "Among these DEGs, we observed that two components of the TFF family (TFF1 and TFF2) were mostly downregulated in gastric cancer cases." (PMID 36428568, 2022). "This suggests that TFF1 and TFF2 play important roles in gastric cancer tumorigenesis and progression." (PMID 36428568, 2022). "In this study, we first identified that TFF1/TFF2 expressions were mediated by DNA methylation in gastric cancer." (PMID 36428568, 2022). "TFF2 expression is found to be markedly decreased in gastric cancer, the downregulation of which was found to be regulated by promoter hypermethylation." (PMID 34885041, 2021). "Emerging evidence has shown that MUC1 and TFF2 play crucial roles in the H. pylori-infected pathogenesis of gastric cancer (GC)." (PMID 32122390, 2020).
gastric cancer (continued). "Downregulation of both Tff1 and Tff2 expression also frequently occurs in gastric cancers displaying tumor suppressor function." (PMID 32231118, 2020). "Suppression of GATA6 in gastric cancer is associated with poor prognosis and likely promotes tumorigenesis by reducing the expression of trefoil factor 1 (TFF1) and trefoil factor 2 (TFF2)." (PMID 29720137, 2018). "In Jiang’s study, TFF2 expression was markedly decreased in gastric cancer, suggesting the role of TFF2 as a tumor suppressor in gastric carcinogenesis and metastasis." (PMID 25876034, 2015). "Down-regulation of TFF-2, suggestive of tumor invasiveness and metastasis, has been recently described in gastric cancers." (PMID 25304323, 2015). "TFF2, as a principal cytoprotective trefoil factor, was mainly expressed in stomach, and the expression was dysregulated during gastric cancer progression." (PMID 25876034, 2015). "On the other hand, TFF2 was shown to possess anti-inflammatory properties and to undergo promoter methylation during gastric cancer progression, data pointing to a tumor-suppressive function." (PMID 24555920, 2014). "In 110 gastric cancer tissue microarray assays, TFF2 expression was downregulated in 82% (90 out of 110)." (PMID 24765170, 2014). "In conclusion, TFF2 expression was markedly decreased in gastric cancer and promoter hypermethylation was found to regulate the downregulation of TFF2." (PMID 24765170, 2014). "The protein expression levels of TFF2 in normal and gastric cancer tissues were verified using western blot analysis." (PMID 24765170, 2014). "Increased expression of trefoil factors contribute to mucosal repair and cell migration and increased levels of TFF2 have been reported in gastric cancer and correlate with reduced survival." (PMID 24533081, 2014). "In the current study, we aimed to define the expression difference of TFF2 in gastric cancer and the gene methylation level." (PMID 24765170, 2014). "In conclusion, the current study showed that the expression levels of TFF2 were downregulated in gastric cancer tissues, particularly in poorly differentiated cancer cells and lymph node-positive tumors." (PMID 24765170, 2014). "The present study used a combination of clinical observations and molecular methods to investigate the correlation between abnormal expression of TFF2 and gastric cancer progression." (PMID 24765170, 2014). "It was reported that TFF2 fulfills an antitumor function by restraining the growth and invasion and enhancing the apoptosis of cancer cells in cholangiocellular carcinoma, gastric cancer, and pancreatic cancer." (PMID 40662145, 2025). "Moreover, a low expression of TFF2 and TFF3, which were predicted to be inhibited by GALNT6, have been reported to associate with gastric cancer." (PMID 36748835, 2023). "TFF2 is expressed at low levels in gastric cancer and is related to methylation." (PMID 37193028, 2023). "Compared with the normal samples, the results demonstrated that ATP4B, TFF2, GIF, GKN1, and TFF2 were low expressed in tumor samples, suggesting these targets might act as the TSGs in gastric cancer." (PMID 36428568, 2022). "Totally, we considered that TFF1 and TFF2 could be the potential DNA methylation biomarkers for gastric cancer." (PMID 36428568, 2022). "Although it has been shown that TFF1 and TFF2 are downregulated in primary gastric cancer, the interaction between TFFs and DNA methylation in gastric cancer remains unknown." (PMID 36428568, 2022). "MUC6 + TFF2 + spasmolytic polypeptide-expressing metaplasia, which may originate from gastric chief cells, is a state of precancerous lesions in gastric cancer." (PMID 34108022, 2021). "TFF2 has been shown to be a poor prognostic marker for gastric cancer." (PMID 34146542, 2021).
gastric cancer (continued). "TFF2 expression is high in the normal gastric mucosa, and several studies have shown that TFF2 expression is downregulated in gastric cancer compared with normal tissue and that this downregulation may be associated with promoter hypermethylation." (PMID 29484116, 2018). "There were two additional SNPs being included, with the runt-related transcription factor 3 gene (RUNX3) related to SPEM formation and intestinal-type gastric cancer, and the trefoil factor 2 (TFF2) gene expressed in SPEM during H. pylori-related gastric carcinogenesis." (PMID 25884934, 2015). "The results suggested that the epigenetic alteration may be involved in the downregulation of TFF2 expression in the progression of gastric cancer." (PMID 24765170, 2014). "In addition, the mRNA levels of TFF2/GAPDH in gastric cancer tissues were significantly lower than those in the corresponding non-neoplastic mucosal tissues (mean ± SE, 3.4±2.7 vs. 9.6±5.4, respectively; P=0.046)." (PMID 24765170, 2014). "TFF2 expression was downregulated in 93% (26 out of 28) of gastric cancer tissue samples compared with the associated non-neoplastic tissues." (PMID 24765170, 2014). "TFF2 mRNA expression in gastric cancer tissues was examined using RT-PCR." (PMID 24765170, 2014). "Furthermore, the promoter hypermethylation of TFF2 was also found in gastric cancer cell lines, AGS and N87, and gene expression was significantly increased following treatment with a demethylating agent, 5-Aza-2′-deoxycytidine." (PMID 24765170, 2014). "However, the overexpression of TFF2 in gastric carcinoma tissues has also been shown in additional previous studies." (PMID 24765170, 2014). "In addition, using the gain of function assay, it was found out that TFF1 and TFF2 could suppress the pathogenesis of gastric cancer." (PMID 36428568, 2022). "Therefore, we considered that TFF1/TFF2 might be the potential DNA methylation target for gastric cancer." (PMID 36428568, 2022). "Totally, TFF1 and TFF2 could be the potential DNA methylation biomarkers for gastric cancer." (PMID 36428568, 2022). "Thus, TFF1 and TFF2 (TFF1/2) are frequently downregulated in gastric cancer." (PMID 27598141, 2016). "Moreover, the average TFF2 methylation level of CpG sites in the promoter region was 70.4% in three gastric cancer tissues, while the level in associated non-neoplastic tissues was 41.0%." (PMID 24765170, 2014). "This bacterium is involved in the DNA methylation of CpG islands of E‐cadherin and tumor‐suppressor genes such as trefoil factor 2 (TFF2) and a forkhead box transcriptional regulator (FOXD3), which drives the development of gastric cancer." (PMID 37530125, 2023). "It was observed that the gastric cancer tissues presented lower TFF1 and TFF2 expressions than normal tissues, and their mRNA expression was negatively related to the DNA methylation level." (PMID 36428568, 2022). "Based on these results, we suspected that TFF1/TFF2 could potentially act as the putative tumor suppressor in GC, and these two TFFs were of great value for predicting the overall survival (OS) status in the gastric cancer cohort." (PMID 36428568, 2022). "We identified REG1A, CHGA, TFF2, ATP4A and ATP4B to be downregulated in intestinal gastric cancer, and Rajkumar and co-workers found ATP4A and ATP4B to be downregulated in gastric tumor tissues compared to normal tissues." (PMID 29484116, 2018). "The serum concentrations of TFF1, TFF2, and TFF3 in the control groups were significantly lower than those in the gastric cancer group with the exception of TFF2 which was elevated in CAG." (PMID 24720760, 2014). "We found that serum concentrations of TFF2 and TFF3 in patients with intestinal type gastric cancer were lower than those in patients with diffuse type." (PMID 24720760, 2014). "The AUC for HP positive gastric cancer patients were significantly larger for TFF3 (0.83, 95% CI [0.73, 0.94]) and PG I/II ratio (0.86, 95% CI [0.74, 0.98]) than those for either TFF1 or TFF2." (PMID 24720760, 2014).
gastric cancer (continued). "This is consistent with the previous studies which demonstrated that high expression of TFF2 was an independent indicator of poor prognosis in CCA and gastric cancer patients with TFF2-expressing tumors had a significantly worse disease-free survival." (PMID 22159958, 2012). "To determine the clinical relevance of the key down-regulated genes in the gastric cancer cohort, we performed a Kaplan–Meier survival analysis and observed that patients with lower TFF1 and TFF2 levels owned shorter overall survival (OS) and tumor-free survival (TFS) time." (PMID 36428568, 2022). "Totally, all these results highlighted the clinical significance of TFFs in gastric cancer and support the idea that TFF1 and TFF2 could be the potential biomarkers for the gastric cancer diagnosis and prognosis." (PMID 36428568, 2022). "With respect to TFF2, spasmolytic polypeptide (TFF2)-expressing metaplasia (SPEM) has been frequently observed in the gastric mucosa surrounding gastric cancer and TFF2 is reported to be down-regulated (83.3%) in primary gastric cancer." (PMID 24720760, 2014). "The results showed that TFF2 mRNA and protein expression were decreased in gastric cancer tissues compared with the matched non-cancerous mucosa, and the decreased level was associated with the differentiation and invasion of gastric cancer." (PMID 24765170, 2014). "In addition, TFF2 promoter hypermethylation was also found in AGS and N87 gastric cancer cell lines." (PMID 24765170, 2014). "We reported that serum TFF1, TFF2, and TFF3 could be good biomarkers for gastric cancer screening." (PMID 28687783, 2017). "However, the expression was significantly reduced in well- and moderately differentiated intestinal gastric cancer tissues, while TFF2 expression was almost absent in the poorly differentiated intestinal and diffuse types of gastric cancer." (PMID 24765170, 2014). "Furthermore, no TFF2 expression was detectable in certain malignant tissues from poorly differentiated gastric cancer patients or highly lymph node-invasive cancer patients." (PMID 24765170, 2014). "The average promoter methylation level of three gastric cancer tissues was 70.4% and the control of non-neoplastic tissues was 41.0%, which showed that gastric cancer tissues with a decreased expression of TFF2 exhibited hypermethylation levels at the 16 CpG sites." (PMID 24765170, 2014). "The concentration of serum TFF2, was significantly lower in patients with intestinal type than diffuse type gastric cancer (0.87 ± 0.07 vs 1.19 ± 0.10, P = 0.0373), but it was not different between early and advanced stages of gastric cancer." (PMID 24720760, 2014). "Therefore, the methylation level of the TFF2 gene promoter was further analyzed in three gastric cancer and non-neoplastic tissue samples, as well as in AGS and N87 gastric cancer cell lines." (PMID 24765170, 2014). "Therefore, the methylation status of cytosines was further analyzed in sites of the TFF2 promoter region of gastric cancer and non-neoplastic tissues, as well as in AGS and N87 gastric cancer cell lines." (PMID 24765170, 2014).